INS (insulin)
Diseases named in the same sentence as INS in open-access papers (continued):
Sharing a sentence is not in itself a finding about the gene and the disease.
Insulin resistance (continued). "In the early conceptualization of MetS, insulin resistance was regarded as its core pathophysiological component, and the syndrome was defined by direct measurements of serum insulin or derived indices such as the Homeostasis Model Assessment of Insulin Resistance (HOMA-IR)." (PMID 41302993, 2025). "Sustained high levels of insulin could promote insulin resistance in the host and contribute to new-onset type 2 diabetes diagnosis even after recovery." (PMID 40572277, 2025). "In summary, the key outcomes include hyperglycemia, hyperinsulinemia, insulin resistance, dyslipidemia, increased inflammation and oxidative stress, and structural changes and changes to the expression of proteins related to insulin signaling and carbohydrate and lipid metabolism in various tissues." (PMID 40426986, 2025). "Among the C19MC miRNAs, 33 showed significant correlations with parameters such as placental weight (25 miRNAs), fetoplacental weight ratio (21 miRNAs), GWG (15 miRNAs), UCP insulin (14 miRNAs), neonatal weight (9 miRNAs) or neonatal insulin resistance (HOMA‐IR; 5 miRNAs)." (PMID 40013652, 2025). "In T2DM, the body’s responsiveness to insulin is reduced, a condition known as insulin resistance." (PMID 41009460, 2025). "Metformin (1000 mg twice a day, 3 months) added to insulin in insulin-resistant overweight or lean adolescents/young adults with T1D improved whole-body insulin resistance, reduced body weight/fat mass and daily insulin dose, and improved vascular health, without affecting HbA1c." (PMID 39998445, 2025). "To summarize, reduction of insulin-stimulated blood flow indicates vascular insulin resistance in T1D in addition to metabolic insulin resistance and this may contribute to abnormal insulin-stimulated glucose disposal in T1D." (PMID 39998445, 2025). "Type 2 Diabetes Mellitus (Type 2 DM) is characterized by chronic hyperglycemia triggered by: - pancreatic β-cell dysfunction that reduces insulin secretion, - insulin resistance leads to increased hepatic glucose production and reduced glucose uptake in liver, muscle, and adipose tissue." (PMID 41282017, 2025). "The infiltration of pro-inflammatory immune cells, such as M1 macrophages, into hypertrophic AT triggers a cascade of inflammatory responses that impair insulin signaling, promote insulin resistance, and contribute to the progression of these metabolic disorders." (PMID 41226298, 2025). "This may diminish the liver’s insulin clearance capacity, leading to insulin resistance and hyperinsulinemia." (PMID 41245406, 2025). "It has been recognized that disorders of insulin signaling occur in cardiovascular and renal cells and play roles in the onset and progression of atherosclerotic diseases in the pathological condition of insulin resistance." (PMID 40943240, 2025). "i-IFG is marked by impaired early-phase insulin secretion and hepatic insulin resistance." (PMID 39977858, 2025). "Clinically, insulin resistance implies that a higher concentration of insulin is necessary to maintain normal glucose levels; thus, it manifests in elevated glucose levels in the blood, resulting in a compensatory increase in pancreatic beta-cell insulin production and hyperinsulinemia." (PMID 40277891, 2025). "Additionally, incorporating fasting insulin measurements into clinical assessments provides valuable insights for predicting and managing conditions related to insulin resistance." (PMID 40002771, 2025). "Type 2 diabetes, on the other hand, is associated with insulin resistance and a relative lack of insulin secretion, and is more common in adults, especially obese people." (PMID 40417223, 2025). "They suggested that this dysregulation could result in abnormal insulin sensitivity and insulin resistance." (PMID 40424446, 2025).
Insulin resistance (continued). "Participants with high levels of plasma glucose (PR: 2.06; 1.03-4.10; P = 0.03) and insulin (PR: 1.57; CI: 1.38-1.79; P < 0.001) exhibited 106% and 57% respective increased prevalence of insulin resistance compared with their counterparts with normal levels of the parameters." (PMID 40273152, 2025). "Altered β-oxidation increases reactive oxygen species production and mitochondrial dysfunction, as well as the accumulation of lipid intermediates, which can interfere with insulin signaling and activate pro-inflammatory pathways, leading to insulin resistance and metabolic syndrome." (PMID 40137162, 2025). "Further investigation into insulin resistance may provide a deeper understanding of the role of insulin in bone health." (PMID 40564223, 2025). "Insulin could also be a key factor in regulating the microbiota, as important differences were observed between the group of obese children with insulin resistance and the group of obese children sensitive to insulin." (PMID 41373658, 2025). "The prolonged administration of insulin may lead to insulin resistance, cerebral atrophy, anorexia, and hepatic steatosis." (PMID 40563879, 2025). "Oxidative stress induces systemic inflammation which can damage body tissues like pancreas, liver and muscles leading to disruption of their functions; these could result in poor insulin secretion, insulin resistance and ultimately frank type 2 diabetes." (PMID 40367203, 2025). "However, when challenged by S961-induced acute insulin resistance, those mice supplemented with glycine or β-alanine had enhanced insulin secretion." (PMID 40260914, 2025). "Blood samples were collected before and after the exercise to measure fasting blood sugar (FBS), insulin, Homeostatic Model Assessment of Insulin Resistance (HOMA-IR), IL-6, and fractalkine levels, allowing for an assessment of the exercise's effects on both groups." (PMID 40091956, 2025). "GLP-1 RAs improve insulin signaling in neurons, which is especially relevant as insulin resistance is increasingly accepted as a shared pathological feature of both Alzheimer’s disease and Parkinson’s disease, with some researchers even referring to AD as “type 3 diabetes”." (PMID 40699685, 2025). "Additionally, the extract showed a decrease in insulin resistance and revealed hypolipidemic effects by reducing levels of plasma insulin, glycemia, triglycerides, and total cholesterol." (PMID 40364361, 2025). "This disruption in insulin signaling leads to insulin resistance and reduced glucose uptake." (PMID 41155203, 2025). "If a pregnant woman’s pancreatic β-cells cannot adequately boost insulin secretion to compensate for this insulin resistance, GDM may develop." (PMID 39796608, 2025). "Fasting glucose and insulin levels can also be used to obtain homeostatic model assessment of insulin resistance (HOMA-IR) and homeostatic model assessment of beta-cell function (HOMA-BETA), which are indices for evaluating the inter-dependence of glucose homeostasis with ketone bodies." (PMID 40004969, 2025). "For example, FGL-1 plays an important role in insulin resistance and T2D by ERK1/2-dependentmechanisms, andFGL-1 up regulation could increase ERK1/2 activity, inhibit insulin signaling and lead to insulin resistance." (PMID 41341131, 2025). "Moreover, pharmacological disruption of the MG53–IRS1 interaction with small‐molecule inhibitors prevents IRS1 degradation, thereby enhancing insulin signaling in muscle cells and improving glucose homeostasis in animal models of insulin resistance." (PMID 41362701, 2025). "In a state of insulin resistance, the insulin signaling pathway is impaired." (PMID 40650120, 2025). "The antihyperglycemic actions of medicinal plants are associated with their ability to modulate glucose metabolism through different pathways, such as restoring β-cell integrity, enhancing insulin-releasing activity, and increasing cellular glucose uptake, which can improve insulin resistance." (PMID 40573309, 2025).
Insulin resistance (continued). "The following subsections delve into the roles and effectiveness of HOMA-IR, fasting insulin, and HbA1c in evaluating insulin resistance, ultimately highlighting their importance in guiding therapeutic interventions and improving outcomes for patients at risk for metabolic complications." (PMID 40002771, 2025). "In addition, since emodin also shows sensitization effects and can improve insulin resistance, it is also expected to become a new insulin sensitizer, providing more treatment options for patients." (PMID 40386230, 2025). "Moreover, TNF-α has been demonstrated to increase glucose and triglyceride production in the liver, meanwhile leading to insulin resistance by a reduction in peripheral glucose uptake in response to insulin." (PMID 40362446, 2025). "However, in those who have obesity or insulin resistance, increased insulin demand leads to an expansion in the number and size of islets and beta cells." (PMID 40722684, 2025). "When insulin resistance increases, the production of insulin by pancreatic β-cells also increases." (PMID 40283630, 2025). "The pathophysiological basis of obesity-associated T2D is closely linked to insulin resistance (IR) and a persistent, low-grade inflammatory state originating in visceral adipose tissue (VAT), which progressively affects other insulin-sensitive organs including liver and skeletal muscle." (PMID 41425544, 2025). "More recent studies have employed dynamic insulin measurements to explore glucoregulatory mechanisms in skeletal muscle and adipose tissue, shedding further light on the relationship between peripheral insulin resistance and CVD." (PMID 40088285, 2025). "This may be because insulin resistance is closely related to hypertriglyceridemia, and Mg, by improving insulin sensitivity, may have indirectly reduced plasma TG levels." (PMID 41462594, 2025). "In 1168 adults and adolescents, primary insulin hypersecretion, independent of insulin resistance, was associated with a worse clinical and metabolic phenotype and this predicted deterioration of glucose control over time." (PMID 41009753, 2025). "The PPARγ targets insulin resistance by promoting peripheral insulin sensitivity, enhancing glucose uptake by skeletal muscle, suppressing liver release of glucose into the bloodstream, and improving the secretory response of insulin by pancreatic β-cells." (PMID 41302107, 2025). "Moreover, PPARG is an important regulatory factor in glucose and lipid metabolism that can improve insulin resistance and enhance the sensitivity of target organs to insulin; thus, PPARG has a role in lowering blood sugar." (PMID 40417668, 2025). "It demonstrates superior diagnostic accuracy for insulin resistance in both patients with and without diabetes and is applicable across all populations, including those receiving insulin therapy." (PMID 40397902, 2025). "There has been speculation that insulin resistance and compromised insulin signaling may play a role in the possible relationship between type 2 diabetes and AD in the central nervous system." (PMID 40381169, 2025). "Insulin resistance refers to the decreased sensitivity of insulin target cells (such as skeletal muscle cells, liver cells, fat cells, etc.)to insulin, that is, the reduced efficiency of glucose uptake and utilization, resulting in abnormal glucose tolerance, etc." (PMID 40661966, 2025). "Importantly, dysregulated insulin signaling—manifesting as insulin resistance or impaired glucose metabolism—is frequently documented after TBI and has been linked to worse neurobehavioral outcomes and prolonged neuronal vulnerability." (PMID 41463131, 2025). "On the one hand, some studies have reported that 5‐HT can increase blood glucose levels and promote insulin resistance; on the other hand, evidence suggests that 5‐HT can stimulate insulin secretion, increase insulin sensitivity, and ameliorate metabolic disorders." (PMID 40937192, 2025).
Insulin resistance (continued). "Elevated ANGPTL8 levels in steatosis/steatohepatitis have been hypothesized to represent a compensatory mechanism to mitigate hepatic insulin resistance and hyperglycemia, potentially via enhanced β-cell proliferation and insulin secretion." (PMID 40276549, 2025). "It has been hypothesised that chemerin exerts its effects on insulin signalling pathways, potentially contributing to insulin resistance through the process of inducing inflammation." (PMID 41301714, 2025). "Chronic hyperglycemia in patients with T2DM leads to peripheral insulin resistance, whereas impaired insulin signaling pathways in the brains of patients with AD lead to “brain insulin resistance,” both of which are closely related to mitochondrial dysfunction and OS." (PMID 40778306, 2025). "In addition to its cardiovascular effects, pheochromocytoma can induce metabolic disturbances, including glucose intolerance and diabetes mellitus, due to catecholamine-induced insulin resistance and suppressed insulin secretion." (PMID 40726849, 2025). "Indeed, insulin resistance appears to develop post–hatch, possibly because of perturbations in the insulin signalling cascade." (PMID 40896492, 2025). "This insulin resistance leads to an increased demand for insulin in pregnant women." (PMID 40045263, 2025). "Patients with type 2 diabetes tend to be older and have other features of insulin resistance, such as obesity, that may necessitate larger amounts of insulin to correct the acidosis." (PMID 40978981, 2025). "The significant pathophysiological features of T2DM are the decrease in the ability of insulin to regulate glucose metabolism (insulin resistance) and the decreased insulin secretion (relative decrease) accompanied by functional deficiency of pancreatic beta cells." (PMID 40692889, 2025). "Insulin resistance is a complicated pathophysiological disorder with an impaired biologic response of the target tissues to insulin stimulation and an impaired ability to inhibit glucose production and stimulate peripheral glucose elimination, often with hyperinsulinemia to maintain normoglycemia." (PMID 40943177, 2025). "Considering the relationship between asprosin levels and insulin resistance, a possible link between inositol and asprosin could be via insulin pathways or they may interact via feedback mechanisms." (PMID 41497562, 2025). "Insulin, a crucial hormone for muscle growth, may be suppressed by insulin resistance, in the state of insulin resistance (IR), the PI3K-Akt-mTOR pathway is impaired, leading to reduced protein synthesis and increased degradation." (PMID 40255379, 2025). "Over time, elevated levels of circulating insulin cause insulin resistance in the body, and the pancreas does not produce enough insulin to overcome the cells' resistance." (PMID 39355932, 2025). "Their livers maintained insulin sensitivity and had elevated Akt phosphorylation and PI3K activity compared to controls, which suggests a causative role of autonomous androgen signaling in the development of PCOS-related hepatic insulin resistance." (PMID 40013621, 2025). "Consequently, this study places its focus on examining the histopathology, mitochondrial dysfunction, and shifts in insulin signaling pathways during the development of insulin resistance, specifically targeting skeletal muscle and myocardium." (PMID 39761309, 2025). "Imidazole propionate is a metabolite produced from the gut microbiota’s metabolism of histidine, which has been linked to insulin resistance and T2DM by disrupting the insulin signaling pathway through activation of the mammalian target of rapamycin complex 1 (mTORC1) in the liver." (PMID 39941139, 2025). "Increased AAAs levels might contribute to the onset of insulin resistance by disrupting the insulin signaling pathways." (PMID 41268578, 2025).
Insulin resistance (continued). "Moreover, the amount of pancreatic fat correlated negatively with beta-cell function parameters (insulinogenic index adjusted for insulin resistance, early glucose-stimulated insulin secretion, beta-cell glucose sensitivity, and rate sensitivity)." (PMID 41009753, 2025). "It is plausible that the increased insulin-staining area reflects the release of insulin to control hyperglycemia in the setting of obesity and insulin resistance, as this group was the only one to exhibit good glycemic control at later time points (18–20 weeks)." (PMID 40394690, 2025). "To (C): Since fasting was previously shown to increase insulin's binding to its receptor, this mechanism may contribute to the decrease of insulin resistance during DF." (PMID 40585323, 2025). "Furthermore, exercise activates AMP-activated protein kinase (AMPK), a key enzyme that enhances insulin signaling and mitochondrial function, collectively improving the body's capacity to regulate blood sugar levels and reduce insulin resistance." (PMID 40533648, 2025). "Previous studies have shown that smokers tend to experience higher insulin resistance than nonsmokers, and smoking cessation has been linked to improved insulin sensitivity." (PMID 40719081, 2025). "TNF-α interferes with insulin signaling promoting insulin resistance." (PMID 40567989, 2025). "Furthermore, dark tea extracts have been reported to improve insulin sensitivity and glucose tolerance by enhancing insulin signaling pathways and reducing peripheral insulin resistance." (PMID 40732991, 2025). "ND6 mtDNA DAMPs (logND6) were associated with greater insulin resistance (HOMA-IR: β = 0.90; SE = 0.40; p = 0.03) and lower insulin sensitivity (Matsuda index: β = −0.86; SE = 0.33; p = 0.01), explaining 64% and 49% of the variance in each outcome, respectively." (PMID 41156500, 2025). "In addition, insulin resistance develops as a result of increased free fatty acids interfering with normal insulin signal transduction." (PMID 40703555, 2025). "The fetal insulin hypothesis suggests that low birth weight and insulin resistance may share a genetic origin, emphasizing insulin’s critical role in fetal development." (PMID 41374021, 2025). "This may disrupt insulin signaling and contribute to insulin resistance, further complicating glycemic control." (PMID 40565075, 2025). "Consistent with LJ3402's suppression of circulating inflammatory cytokines (TNFα and IL‐1β), LJ3402 administration mitigated age‐related insulin resistance and impaired thermoregulation, as demonstrated by improved glucose and insulin tolerance and increased cold resistance." (PMID 41346200, 2025). "Type 2 diabetes (T2D) is characterized by insulin resistance and defective insulin secretion." (PMID 40074175, 2025). "Notably, during insulin-stimulated conditions, all investigated types of insulin resistance showed enhanced BGM." (PMID 39185744, 2025). "Experimental studies in mice suggest that insulin promotes magnesium reabsorption in the TAL; therefore, insulin resistance or deficiency in T2DM may diminish this stimulatory effect and exacerbate magnesium loss." (PMID 40964237, 2025). "For insulin resistance, measures such as improving lifestyle (e.g., reasonable diet, appropriate exercise) and using insulin sensitizers can be taken to enhance insulin sensitivity and optimize insulin signal transduction efficiency." (PMID 41341139, 2025). "Therefore, this study aimed to systematically assess the efficacy of M. charantia compared with placebo or active controls on FBG, HbA1c, insulin, homeostatic model of insulin resistance (HOMA-IR) and HOMA-β in adults with prediabetes or type 2 diabetes." (PMID 41280283, 2025). "Additionally, TNF‐alpha reduces adiponectin secretion, a hormone that improves insulin sensitivity, further contributing to insulin resistance." (PMID 40551726, 2025). "The Matsuda Index correlates with insulin sensitivity and may be useful for detecting insulin resistance in CF patients." (PMID 41300682, 2025).